MMP9 (matrix metallopeptidase 9)
Diseases named in the same sentence as MMP9 in open-access papers (continued):
Sharing a sentence is not in itself a finding about the gene and the disease.
glioma (continued). "MMP9 upregulation was predictive of poor prognosis in patients with lung cancer, glioma or colorectal cancer." (PMID 27777384, 2016). "Next, we employed two independent glioma gene expression dataset (REMBRANDT and GSE16011 datasets) to examine the association between MMP9 expression level and glioma grade." (PMID 27022952, 2016). "miR-491-5p were demonstrated to be negatively correlated with the expression of MMP-9 protein and reduced invasive ability of U251 and U87 glioma cell lines." (PMID 27905892, 2016). "The correlation of MMP9 expression with tumor progression was explored in glioma specimens of all grades." (PMID 27022952, 2016). "Previous studies have performed experiments to examine the mechanism through which MMP9 affectes the survival of the glioma patients." (PMID 27022952, 2016). "The infection led to increased MMP-9 levels in C6 glioma cells and specific inhibition of MMP-9 by SB-3CT augmented bacillary clearance when used along with antitubercular drugs." (PMID 27899068, 2016). "MMP-9/NGAL activity was detected in 85.7% of glioma patients and was positively correlated with the activity of MMP-9 and MMP-9 Dimer in Preop-1d urine (Spearman's r = 0.83, r = 0.74, resp.; p < 0.05)." (PMID 26663949, 2015). "Here, we compared the clinical characteristics of glioma patients with the MMP-9/NGAL activity measured in their respective tumor and urine samples." (PMID 26663949, 2015). "For example, simultaneous RNAi-mediated depletion of MMP-9 and uPAR significantly reduces the migratory capacity of glioma cells." (PMID 26663949, 2015). "Several lines of evidence show that MMP-9 can play direct and indirect roles in glioma tumorigenesis." (PMID 26663949, 2015). "There is a strong correlation between elevated MMP levels, such as MMP-2 and MMP-9 and tumor cell invasiveness in glioma." (PMID 26305187, 2015). "All in all, our above results showed that GCN5 was upregulated in human glioma tissues and was associated with PCNA and MMP9 expression." (PMID 26378521, 2015). "A previous study reported that the up-regulation of miR-885-5p reduced the levels of MMP-9 in glioma cells and that it inhibited cellular invasion." (PMID 26090613, 2015). "Other metalloproteinases, e.g. MMP-9, were among the genes most upregulated by RCCS 3D culture, consistent with a significant association between VM and MMP-9 expression in clinical glioma specimens and in tumor / endothelia co-cultures." (PMID 26203665, 2015). "MMP-2 and MMP-9 are overexpressed in experimental glioma models and patient tissue samples and play an important role in glioma progression, particularly in tumor invasion." (PMID 26663949, 2015). "The roles of specific NF-κB proteins in regulating glioma cell invasion and expression of Matrix Metalloproteinase 9 (MMP9) in response to TWEAK were evaluated using shRNA-mediated loss-of-function studies." (PMID 25622756, 2015). "IDH1 mutation downregulated glioma cell proliferation by blocking the cell cycle, reduced the cell invasion ability via MMP-2 and MMP-9 downregulation and promoted the cell migration ability." (PMID 24520288, 2014). "Both MMP-2 and MMP-9 have independently been found to be down-regulated after treatment with pioglitazone, suggesting the role of PPARγ agonists in reducing glioma cell invasiveness." (PMID 24672773, 2014). "A previous study demonstrated that the downregulation of MMP-9 expression in glioma cells significantly decreases their migration and invasiveness." (PMID 24642531, 2014). "The comprehensive analyses of GFAP and MMP-9 expression levels, and invasion ability indicated that the cell lines from glioma tissues of different pathological grades showed obvious variations in malignant behavior." (PMID 25163530, 2014).
glioma (continued). "In a study specifically seeking to identify microRNAs regulating MMP-9, fourteen positive and thirty one negatively correlating microRNAs were identified of which miR-491-5p was found to not only directly target MMP-9, but also supress glioma cell invasion." (PMID 24670365, 2014). "To validate in vivo the described results, we performed MMP9 immunostaining of brain tissue sections from human glioma U-87 MG-intracranial bearing mice treated with aflibercept for 6 weeks and then presenting an invasive phenotype." (PMID 24809734, 2014). "This study was designed to evaluate atorvastatin effects on plasma MMP-9 concentration in neurosurgical- induced brain injuries after glial tumor resection." (PMID 24397933, 2014). "Both the MMP-9 immunohistochemical staining and the transwell experiment were used to assess the invasion abilities of glioma cells." (PMID 25163530, 2014). "Our recent studies clearly demonstrated the involvement of α9β1 integrin in MMP-9-/uPAR-mediated glioma cell migration." (PMID 24325546, 2013). "A prominent reduction of iNOS expression was observed in the tumor regions of nude mice brains, which were injected with 5310 glioma cells, after MMP-9 and/or uPAR knockdown." (PMID 24325546, 2013). "In the present study, we evaluated the involvement of α9β1 integrin-iNOS pathway in MMP-9- and/or uPAR-mediated glioma cell migration." (PMID 24325546, 2013). "Propentofylline (PPF), an atypical methylxanthine and glial modulating agent with anti-inflammatory actions, was also shown to be effective in reducing glioma growth by targeting microglia and possibly decreasing their expression of MMP-9." (PMID 23864876, 2013). "On the other hand, MMP-9 and IL-8, both of which are downstream target genes of NF-κB, have also been found to be upregulated in glioma cells." (PMID 23383216, 2013). "Our recent studies have clearly demonstrated the role of α9β1 integrin in matrix metalloproteinase-9 (MMP-9) and/or urokinase plasminogen activator receptor (uPAR)-mediated glioma cell migration." (PMID 24325546, 2013). "MMP-9 and uPAR shRNAs and overexpressing plasmids were used to downregulate and upregulate these molecules, respectively in U251 glioma cells and 5310 glioma xenograft cells." (PMID 24325546, 2013). "Furthermoe, the levels of several NF-κB target genes, TNF-α, IL-6, CCND1, MYC, BcL-XL and MMP-9, were upregulated in Bmi-1-overexpressing, but downregulated in Bmi-1-silenced glioma cells." (PMID 23383216, 2013). "In vitro study revealed that blocking of MMP-2 and MMP-9 resulted in inhibition of human malignant glioma cell invasion, indicating that MMP-2 and MMP-9 play an important role in the metastasis and invasion of glioma cells." (PMID 23593320, 2013). "Here, we show that the constitutive MMP-2 expression and activity were higher than that of MMP-9 for both glioma cell lines." (PMID 23533307, 2013). "MMP-2 and MMP-9 are two important members, which play important roles in the invasion and malignancy of glioma cells." (PMID 23593320, 2013). "Here, we investigated the effect of rSAA on the expression and activity of MMP-2 and MMP-9 in two human glioma cell lines, A172 and T98G, and the correlation with cell proliferation, migration, and invasion." (PMID 23533307, 2013). "In the present study, we investigated the involvement of the α9β1 integrin-iNOS pathway in MMP-9- and/or uPAR- mediated glioma cell migration." (PMID 24325546, 2013). "The expression of NFAT1 was significantly correlated with that of COX-2 (R = 0.209, P<0.05), MMP-7(R = 0.404, P<0.01) and MMP-9 (R = 0.414, P<0.01) in gliomas." (PMID 23762456, 2013). "MMP-9 and/or uPAR gene silencing also reduced invasive/migratory potential and growth of glioma cells." (PMID 24325546, 2013). "In summary, glioma cells expressing MMP-9 and/or uPAR utilize α9β1-iNOS pathway to mediate cell migration." (PMID 24325546, 2013).
glioma (continued). "MMP-2 and MMP-9 contribute most in the malignancy of gliomas among other MMPs and are highly expressed in glioma tissues." (PMID 23593320, 2013). "MMPs are essential for proper ECM remodeling and invasion while MMP-2 and MMP-9 are known to be overexpressed in gliomas." (PMID 23533307, 2013). "RT-PCR analysis revealed elevated iNOS mRNA expression in either MMP-9 or uPAR overexpressed glioma cells." (PMID 24325546, 2013). "The invasion of glioma CSCs (GSCs) in zebrafish embryos was markedly inhibited by an MMP-9 inhibitor." (PMID 23613942, 2013). "The migration potential of MMP-9- and/or uPAR-overexpressed U251 glioma cells was significantly inhibited after treatment with L-NAME, an inhibitor of iNOS." (PMID 24325546, 2013). "We also showed that artemether significantly promoted the apoptosis of U87 cells and inhibited the expressions of MMP-2 and MMP-9, which are the two major proteolylic enzymes involved in the invasion and metastasis of gliomas." (PMID 23593320, 2013). "Taken together, these data suggested that overexpression of Bmi-1 upregulated and activated MMP-9 in glioma cells in vitro." (PMID 22967049, 2012). "Matrix metalloproteinase-9 (MMP-9), a member of the matrix metalloproteinase class of gelatinases, plays essential roles in the invasiveness of glioma cells, mainly by catalyzing the destruction of basal membrane and extracellular matrix." (PMID 22967049, 2012). "Correlation studies in glioma specimens showed that Bmi-1 expression significantly correlated with the expression of MMP-9 (P < 0.01)." (PMID 22967049, 2012). "The pivotal role of MMP-9 in enhancing glioma tumor migration, invasion and angiogenesis has already been well studied." (PMID 23183822, 2012). "We found that the overexpression of miR-211 in glioma cell lines retards MMP-9 activity, induces apoptosis and DNA damage response (DDR)." (PMID 23183822, 2012). "MMP-9, one member of the MMP family, is upregulated and associated with progression and poor prognosis in glioma." (PMID 22967049, 2012). "Earlier studies also showed that the siRNA-mediated knockdown of MMP-9 expression in glioma cells induces apoptosis and inhibits tumor growth." (PMID 23183822, 2012). "According to their results, 14 miRNAs (including miR-143, miR-210 and miR-214) positively regulate the overexpression of MMP-9 in glioma cell lines we tested (U87 and U251)." (PMID 22490015, 2012). "It has been suggested that VEGF released from the extracellular matrix by MMP9 mediates the recruitment of bone marrow-derived PPCs as well as EPCs to glioma, thereby promoting angiogenesis." (PMID 24213237, 2012). "In the present study, we investigated the functional role of miR-211 in inducing glioma cell apoptosis via suppression of MMP-9." (PMID 23183822, 2012). "It has been shown that downregulation of MMP-9 in glioma cells reduces the levels of proteins which play a direct role in regulating telomere length." (PMID 23209831, 2012). "Two miRNAs, miR-885-5p and miR-491-5p, were determined to reduce the level of MMP-9 and inhibit cellular invasion in U251 and U87 glioma cells." (PMID 23183822, 2012). "Taken together, these results indicated that Bmi-1 promoted the transactivation activity of the NF-kappaB binding site present in the MMP-9 promoter in glioma cells." (PMID 22967049, 2012). "We found an acute inhibitory effect of miR-211 on glioma cell invasion and migration via suppression of MMP-9." (PMID 23183822, 2012). "Knockdown of Bmi-1 also significantly decreased the expression and activity of MMP-9 in glioma cells when compared with vector-control cells." (PMID 22967049, 2012). "Collectively, these results indicated that the overexpression of Bmi-1 induced an aggressive phenotype in glioma cells by activating NF-kappaB signaling, leading to the upregulation of the NF-kappaB target gene MMP-9." (PMID 22967049, 2012).
glioma (continued). "ELISA and the gelatin zymography assay confirmed that overexpression of Bmi-1 increased MMP-9 expression and activity in glioma cells." (PMID 22967049, 2012). "Since miR-211 levels inversely correlate with MMP-9 protein levels, we examined the expression levels of MMP-9 in miR-211 and IR-treated glioma CSC using RT-PCR and immunoblot analyses." (PMID 23183822, 2012). "In conclusion, this study demonstrates that Bmi-1 is upregulated and promotes an aggressive phenotype in glioma via activation of the NF-kappaB signaling pathway, leading to increased MMP-9 expression and activity." (PMID 22967049, 2012). "The siRNA-mediated knockdown of MMP-9 expression has also been shown to induce Caspase-9-mediated apoptosis in glioma cells." (PMID 23183822, 2012). "Since the overexpression of miR-211 suppressed MMP-9 protein and showed inverse correlation, we investigated further the miR-211 role in glioma cell migration and invasion." (PMID 23183822, 2012). "The expression of MMP-2 and MMP-9 in the glioma specimens was observed in the tumor cellular cytoplasm, the vascular endothelial cells and the basement membranes." (PMID 23554622, 2010). "Selective gene suppression of MMP-2 or MMP-9 dramatically reduces the invasive phenotype of gliomas." (PMID 20587068, 2010). "Both the latent and active forms of MMP-2 and the latent form of MMP-9 were detected in the culture supernatant from glioma cells." (PMID 20587068, 2010). "In the low grading gliomas, quantitative analysis revealed the mean expression levels of MMP-2 and MMP-9 staining were 16.38±8.43% and 12.09±7.98%, respectively, compared to those of 60.47±21.45% and 41.03±14.00% in the high grading gliomas." (PMID 23554622, 2010). "The present study showed that MMI-166 reduced the activities of MMP-2 and MMP-9 and significantly inhibited the invasive and angiogenic activities of glioma cells in vitro and in vivo." (PMID 20587068, 2010). "Growth factors generally up-regulated MMP-2 and MMP-9 expression in the gliomas but were least effective in the meningioma; the effect being most prominent with TGF-β1 and TGF-β2 in all the cell lines." (PMID 10638966, 2000). "For instance, targeting MMP-9 in conjunction with immune checkpoint inhibitors could potentially enhance immune cell infiltration and activity within glioma tumors." (PMID 40265458, 2025). "Alternately, the generation of MMP-9 and vimentin was increased by Snail in the glioma cell lines." (PMID 40575155, 2025). "IHC analysis of rat brain tissues revealed that the expression levels of Ki67 (a marker of cell proliferation) and matrix metalloproteinase‐9 (MMP9, an indicator of cell invasion ability) were significantly higher in the Glioma group than in the Sham group (p < 0.001)." (PMID 41363048, 2025). "MMP-9 levels fell below the cut-off value in 49 healthy subjects and 27 glioma patients." (PMID 40512281, 2025). "Among these, MMP2 and MMP9 are gelatinases that contribute to glioma progression." (PMID 40759869, 2025). "Therefore, we investigated the effects of Calanquinone A on MMP2 and MMP9 expression in glioma cells." (PMID 40759869, 2025). "In addition, there was an aberrant 44-fold increase of MMP-9 in the glioma microenvironment when compared to healthy controls." (PMID 41034696, 2025). "MMP-9 is also expressed in microglia, which contribute to glioma invasiveness." (PMID 41573658, 2025). "Sixty glioma-associated targets were associated with CHR, such as MDR transporters (ABCB1, ABCC1, ABCG2), cyclin-dependent kinases (CDK1, CDK6), matrix metalloproteinases (MMP2, MMP9, MMP12), and genes related to inflammation or oxidative stress (NOS2, NOX4)." (PMID 40963691, 2025). "Taken together, these data demonstrate that significant P2X7R expression in high-grade glioma samples was positively associated with VEGFB expression, and inversely associated with IL-4, IL-8, MMP-9 and PCNA, demonstrating a potentially pro-tumour angiogenic capacity." (PMID 41034696, 2025).
glioma (continued). "Still only BMP2, MMP13, MMP2, LCK, MMP9, and AR have been reported to affect the glioma invasion." (PMID 39458959, 2024). "Additional support may be inferred from other findings in this study, where increased MMP-2 and MMP-9 levels under NF-κB regulation suggest that low NaF concentrations in U-87 glioma cells might promote adverse NF-κB activation." (PMID 39684484, 2024). "Over the years, it was widely demonstrated that the activation of the SLC22A17 gene partners (NGAL and MMP-9) may promote different malignancies, including glioma, endometrial cancer, lung adenocarcinoma, and gastric cancer." (PMID 39358721, 2024). "SLC39A1 could foster the MMP2/MMP9 expression and glioma cell proliferation and its expression is correlated to the pathological grade, IDH mutational status, and 1p19q co-deletion." (PMID 39012280, 2024). "MMP2 and MMP9 play important roles in GBM invasion and are associated with glioma malignancy." (PMID 38906916, 2024). "Treatment of SMA-560 cells with 40 μM NS1643 reduced MMP-9 secretion over a 24 h period suggesting NS1643 may reduce the invasivity of glioma." (PMID 39240809, 2024). "SRC‐1 directly binds PEA3 and binds to VEGF and MMP‐9 promoter in glioma cell." (PMID 38506084, 2024). "Furthermore, an uptick in MMP2/9 was observed within the hsa-miR-134-5p mimic groups, suggesting an inhibition of glioma cell cycle progression influenced by hsa-miR-134-5p’s suppression of MMP2/MMP9." (PMID 38579169, 2024). "M1-AQP4 played a crucial role in mediating the invasive capabilities of glioma cells, and intriguingly the increased invasiveness has been found to be induced by the increase of MMP-9 activity, which has been shown to play a critical role in the mechanisms of glioma invasion." (PMID 39247976, 2024). "Expression of MMP-2 and MMP-9 positively correlates with glioma grade." (PMID 38969910, 2024). "The predictive model constructed using four genes involved in macrophages and cancer cells, namely POSTN, CHI3L1, SAA1, and MMP9, holds promise in distinguishing high inflammation-hypoxia-immunosuppression microenvironment signatures and helps optimize trametinib selection for glioma treatment." (PMID 39574472, 2024). "Similarly, it has also been shown that the inhibition of MMP2 and MMP9 by EFEMP2 knockdown resulted in a reduction in glioma invasion." (PMID 39458959, 2024). "It has been shown that miR-34a inhibits MMP9 expression and suppresses the migration of glioma." (PMID 38655096, 2024). "Glycitein down-regulates the expression of MMP3 and MMP9 to inhibit glioma cell invasion." (PMID 39338323, 2024). "High invasiveness of gliomas is associated with the expression activity of MMP-2 and MMP-9." (PMID 39877386, 2024). "Among the several MMPs involved in glioma progression, MMP-9 has been extensively studied." (PMID 38969910, 2024). "MMP9 expression is also correlated with glioma grade and correlated with survival outcomes." (PMID 38906916, 2024). "However, Rictor, a component of the mTOR complex, induces glioma cell migration, increasing MMP-9 expression through the Raf-1-MEK-ERK signaling pathway." (PMID 36980765, 2023). "Moreover, rhSHH upregulates MMP-2 and MMP-9 expression and protein levels, while cyclopamine downregulates mRNA and protein concentrations in glioma U251 cells." (PMID 38069210, 2023). "Moreover, antioxidants quercetin (QE), baicalein (BE) and myricetin (ME) effectively downregulated ROS and MMP9 and inhibited glioma cell invasion/migration events in vitro." (PMID 38130720, 2023). "In addition, MMP-9 was downregulated in glioma cells stimulated by 12-O-tetradecanoylphorbol-13-acetate (TPA) plus KPF-BBR and TPA+KPF-ABR compared with the TPA-treated cells." (PMID 37445894, 2023). "Mangiferin targeted the inhibition of MMP-9 and may, therefore, provide an effective pharmacological strategy for treating gliomas." (PMID 38137424, 2023).